AFF3 (ALF transcription elongation factor 3)
Description:
Putative transcription activator that may function in lymphoid development and oncogenesis. Binds, in vitro, to double-stranded DNA.
Synonyms: LAF4; MLLT2-like; KINS
Tractability: PROTAC: ubiquitination databases record sites on it; its protein half-life has been measured.
Gene: Protein-coding gene on chromosome 2 (99,545,419 to 100,192,428, reverse strand). Ensembl gene ENSG00000144218.
Subcellular location: Nucleus
Subcellular location (Human Protein Atlas): Nucleoplasm; Cytosol
Gene Ontology:
Molecular function: transcription coregulator activity
Biological process: embryonic hindlimb morphogenesis; response to tumor necrosis factor; DNA-templated transcription elongation; nervous system process; regulation of DNA-templated transcription; regulation of gene expression
Cellular component: nucleoplasm; nucleus; super elongation complex
Genetic constraint (gnomAD): Loss-of-function variants: 30 observed, 127.95 expected, observed/expected ratio (o/e) 0.23, 90% interval 0.17 to 0.32. The upper end of that interval is the gene's LOEUF score, 0.32, which puts it in group 1 of 6, group 1 being the genes least tolerant of losing a copy. Missense variants: 1,369 observed, 1,618.6 expected, observed/expected ratio (o/e) 0.85, 90% interval 0.81 to 0.88. Synonymous variants: 642 observed, 643.14 expected, observed/expected ratio (o/e) 1, 90% interval 0.94 to 1.07.
Homologues: Orthologues: macaque AFF3 (98% identical), chimpanzee AFF3 (98% identical), dog AFF3 (93% identical), pig AFF3 (90% identical), mouse Aff3 (88% identical), rat Aff3 (88% identical), rabbit AFF3 (86% identical), guinea pig AFF3 (73% identical), tropical clawed frog AFF3 (39% identical), Drosophila melanogaster lilli (22% identical). Paralogues in human: AFF2 (39% identical), AFF4 (34% identical), AFF1 (31% identical).
Diseases named in the same sentence as AFF3 in open-access papers:
AFF3 is named in the same sentence as 67 diseases in open-access papers, as found by Europe PMC text mining. Sharing a sentence is not in itself a finding about the gene and the disease. The quoted sentences say what the papers report.
breast carcinoma (14 papers, 2011 to 2024). "High AFF3 expression in ER+ breast cancer was linked to a poor overall survival rate, and upregulation of AFF3 underlies tamoxifen resistance in ER+ breast cancer." (PMID 36439479, 2022). "AFF3 was positively associated with faster disease progression in luminal breast cancer (P = 0.008)." (PMID 30326937, 2018). "Overexpression of AFF3 in breast cancer was associated with tamoxifen resistance and worse OS." (PMID 33224957, 2020). "AFF3 has recently been discovered to play a significant role in the initiation and growth of several malignancies, including glioma, breast cancer, and adrenocortical carcinoma." (PMID 38361095, 2024). "Fusion partners of FGFR2 reported specifically in breast cancer are AFF3, CASP7 and CCDC6, while partners identified in other cancers include TACC and KIAA family members, PPHLN1, NTRK1, BICC1, AHCYL1, OFD1 and SLC45A3." (PMID 34344433, 2021). "We demonstrate that AFF3 is upregulated in breast cancers, leading to tamoxifen resistance and estrogen-independent growth, which are properties more consistent with an oncogene." (PMID 30326937, 2018). "The present study demonstrates for the first time that AFF3 mediates tamoxifen resistance and estrogen-independent growth in breast cancer." (PMID 30326937, 2018). "We investigated AFF3 expression in breast cancer cells and in clinical breast cancer specimens with western blot and Real-time PCR." (PMID 30326937, 2018). "In this study, we show that AFF3 is overexpressed in ER+ human breast cancers, leading to tamoxifen resistance and estrogen-independent growth, and that patients with primary breast cancers with AFF3 overexpression have worse survival." (PMID 30326937, 2018). "We also examined the effects of AFF3 knockdown and overexpression on breast cancer cells using luciferase, tetrazolium, colony formation, and anchorage-independent growth assays in vitro and with nude mouse xenografting in vivo." (PMID 30326937, 2018). "Third, AFF3 upregulation in two separate ER+ breast cancer cell lines led to tamoxifen resistance, and gene knockdown by stable shRNA reversed this phenotype." (PMID 30326937, 2018). "Quantitative real-time reverse transcription-PCR (qRT-PCR) and western blotting confirmed that AFF3 expression was increased in ER+ breast cancer cell lines." (PMID 30326937, 2018). "AFF3 overexpression in breast cancer cells resulted in tamoxifen resistance, whereas RNA interference–mediated gene knockdown reversed this phenotype." (PMID 30326937, 2018). "To verify that AFF3 upregulation was also present in actual human breast cancers, we evaluated specimens from three normal breast tissues and 10 ER+ breast cancer tissues." (PMID 30326937, 2018). "qRT-PCR and western blotting showed that AFF3 was upregulated in the ER+ breast cancer tissues compared to the normal breast tissues." (PMID 30326937, 2018). "AFF3 upregulation mediates tamoxifen resistance and estrogen‐independent growth in breast cancer." (PMID 36597889, 2023). "Interestingly, the effect of AFF3 on prostate cancer appears to be the inverse of that on ER+ breast cancer, implying that AFF3 in androgen and estrogen metabolism warrants additional exploration." (PMID 36439479, 2022). "To determine the clinical significance of AFF3 overexpression in human breast cancers, we assessed AFF3 protein levels through immunohistochemical staining on an independent cohort of 101 formalin-fixed, paraffin-embedded tumor tissues from patients with liminal breast cancer." (PMID 30326937, 2018). "Notably, AFF3 expression was increased in luminal A and luminal B breast cancers, whereas SLC16A14 expression levels appeared unchanged." (PMID 30326937, 2018). "Aberrant expression of the AFF3 gene itself in mammary epithelial cells could have a similar effect and thereby contribute to the pathogenesis of breast cancer." (PMID 30326937, 2018).
breast carcinoma (continued). "Although AFF3 was never associated to breast cancer, it was recently proposed to play a pivotal role in adrenocortical carcinoma." (PMID 28241739, 2017). "In addition to the five, three other TFs among the top 15 identified by InPheRNo have modest literature support for a role in BRCA development: AFF3 is a nuclear transcriptional activator, which is abnormally expressed in some cases of breast cancer and has been suggested as a proto-oncogene." (PMID 33558504, 2021). "Therefore, the discovery of a previously unidentified gene, AFF3, and its functional role in drug resistance, may lead to improved systemic therapies and predictive markers for treating ER+ breast cancers." (PMID 30326937, 2018). "b Real-time PCR analysis and western blot analysis of AFF3 expression in normal breast cell MCF10A and breast cancer cell lines, including BT-549, HCC1937, MDA-MB231, MDA-MB468, MDA-MB361, T47D, MCF-7, MDA-MB-415." (PMID 30326937, 2018). "Expression of TBC1D9 and CEACAM6 was higher in GATA3 mutant MCF-7 cells, GATA3 mutant CAMA1 cells, and primary GATA3 mutant breast cancer cells, whereas expression of PPT1, CYBRD1, HOXC13, and AFF3 was higher in GATA3 wild type cells." (PMID 29262572, 2017). "d Real-time PCR analysis of AFF3 expression in breast cancer tissues compared with noncancerous breast tissues." (PMID 30326937, 2018). "S1.a Expression level of AFF3 and SLC116A14 in breast cancer tissues compared with noncancerous breast tissues (n = 627; TCGA)." (PMID 30326937, 2018).
Intellectual disability (11 papers, 2014 to 2025). "AFF3 is also a new promising candidate gene that was previously associated with intellectual disability and cellular migration in the cerebral cortex." (PMID 36449109, 2023). "To date, AFF3 deletions and missense variants have been identified in 18 individuals with developmental delay and intellectual disability." (PMID 35615272, 2022). "Besides developmental delay and intellectual disability, most patients carrying AFF3 variants presented with encephalopathy, skeletal dysplasia, failure to thrive, microcephaly and global brain atrophy." (PMID 35615272, 2022). "Copy number variations in NIPA1 were found in psychiatric disorders, KIAA1211L was identified in a schizophrenia twin-study and is a candidate gene for opioid abuse, and AFF3 is involved in intellectual disability and cellular migration in the cerebral cortex of mice." (PMID 33004014, 2020). "Laf4/Aff3, a member of the AFF (AF4/FMR2) family, is known as a putative transcription factor and silencing of this gene is associated with neurodevelopmental disorders and intellectual disability (ID)." (PMID 26733777, 2015). "Since MDGA2 is a target of the AF4/AFF member 3 (LAF4/AFF3) transcription factor and its overexpression partially rescues phenotypes caused by LAF4/AFF3 deficiency, MDGA2 may also mediate LAF4/AFF3 deletion-caused neurodevelopmental defects and intellectual disability." (PMID 40168357, 2025). "ALF transcription elongation factor 3 (AFF3), also known as MLLT2-like, LAF4, and KINS, belonged to the AF4/FMR2 family and encoded a nuclear protein involving multiple biological processes, including autoimmune diseases, tumorigenesis, intellectual disability, horseshoe kidney, and so on." (PMID 38886730, 2024). "Many of these genes have been previously implicatedwith human phenotypes, including developmental delay (e.g. ASPM, AFF3 and MAPT) and intellectual disability (e.g. NEMF, PI4KA and KANSL1)." (PMID 31757203, 2019).
adrenocortical carcinoma (6 papers, 2015 to 2024). "AFF3 is a mediator of the oncogenic effects of β‐catenin involved in adrenocortical carcinoma, acting on transcription and RNA splicing." (PMID 36597889, 2023).
autoimmune disease (4 papers, 2012 to 2024). A disorder resulting from loss of function or tissue destruction of an organ or multiple organs, arising from humoral or cellular immune responses of the individual to their own tissue constituents. "Furthermore, studies have shown that the AFF3 gene was initially linked to type 1 diabetes (T1D), and then, later, its role was determined in 16 different autoimmune diseases including RA and SLE." (PMID 34104118, 2021). "It is of note that AFF3, which also belongs to the AF4/FMR2 family, is associated with susceptibility to autoimmune diseases." (PMID 22291604, 2012).
Autoimmunity (4 papers, 2019 to 2025). The occurrence of an immune reaction against the organism's own cells or tissues. "The AFF3 gene encodes a DNA interacting nuclear factor having a transcriptional activation domain that makes it a strong candidate gene in autoimmunity." (PMID 34104118, 2021). "This property of the AFF3 gene has made it a strong candidate for autoimmunity in the human cell." (PMID 34104118, 2021). "Like in panel, I autoimmunity appears to be in play with proteins AFF3, SMYD3, and LRP1." (PMID 31026304, 2019). "Notably, IKZF3 and AFF3, transcriptional regulators of lymphocyte differentiation, have been recognized in European and Middle Eastern cohorts, reinforcing their cross-population relevance to autoimmunity and fibrosis." (PMID 41283471, 2025).
developmental delay (4 papers, 2014 to 2022). "For example individuals AII.3 and AII.4 both have >300 repeats and had evidence of neurodevelopmental delay during childhood but have lower levels of methylation than BI.2 (∼120 repeats, biallelic expression of AFF3) and C1.2 (106 repeats) neither of whom showed evidence of developmental delay." (PMID 24763282, 2014).
diabetes (4 papers, 2011 to 2024). "Interestingly, recent studies showed an association of AFF3 locus with triglyceride levels and the end-stage renal disease as a major complication of diabetes." (PMID 27092776, 2016).
leukemia (4 papers, 2011 to 2025). A malignant (clonal) hematologic disorder, involving hematopoietic stem cells and characterized by the presence of primitive or atypical myeloid or lymphoid cells in the bone marrow and the blood. "Association to rs9653442 on 2q11 may indicate the role of locus AFF3 which encodes nuclear protein LAF-4 with homology to a protein involved in leukemia development and a possible function in lymphoid ontogenesis." (PMID 22654555, 2011). "The parent gene, Aff3, is located in a genetically variable region, and it can be excised via intron 5 to form a replicable transposon that translocates to other chromosomes, potentially contributing to leukemia." (PMID 40315012, 2025). "Specific MLL TPGs are detected exclusively in leukemias of the lymphoid (e.g., LAF4/AFF3) or of the myeloid lineages (e.g., SEPT6)." (PMID 30815012, 2019). "Lymphoid nuclear protein related to AF4 (LAF4, also known as AFF3) is one of an estimated 40 genes that can form such MLL fusions, although LAF4 is one of the few genes that is aberrantly translocated in both B- and T-cell derived leukemia." (PMID 25162227, 2014).
rheumatoid arthritis (4 papers, 2015 to 2025). A chronic, systemic autoimmune disorder characterized by inflammation in the synovial membranes and articular surfaces. "AFF3 is an immunoglobulin class switch factor that has been shown to be a susceptibility factor for rheumatoid arthritis, and H19 has been shown to regulate ISG expression in macrophages in response to lipopolysaccharide stimulation." (PMID 39415484, 2025). "This study was designed to detect the association of a single-nucleotide polymorphism (SNP) rs10865035 in the AFF3 gene with the genetic background of rheumatoid arthritis (RA) in the Pakistani cohort." (PMID 34104118, 2021). "Pathway analysis of the DEGs did not identify any IFN‐related pathways, but AFF3 and H19, which are two of the most significant DEGs, have tentatively been implicated in immune responses in other autoimmune conditions including rheumatoid arthritis." (PMID 39415484, 2025). "In our study, there were six novel loci outside of this region where genetic variation may influence rheumatoid arthritis risk via changes in DNA methylation (TTC34, MMEL1, AFF3, IRF5, CXCR5 and PGAP3)." (PMID 29893838, 2018).
acute lymphoblastic leukemia (3 papers, 2014 to 2025). Leukemia with an acute onset, characterized by the presence of lymphoblasts in the bone marrow and the peripheral blood. "The AFF (AF4/FMR2) family of genes includes four members: AFF1 (or AF4, acute lymphoblastic leukemia-1 fused gene from chromosome 4), AFF2 (or FMR2, Fragile X mental retardation 2), AFF3 and AFF4 (or AF5Q31, acute lymphoblastic leukemia-fused gene from 5q31)." (PMID 26214578, 2015). "The AFF (AF4 (ALL1 (acute lymphoblastic leukemias)-fused gene from chromosome 4)/FMR2 (fragile X mental retardation 2)) family of genes includes four members: AFF1/AF4, AFF2/FMR2, AFF3/LAF4 and AFF4/AF5q31." (PMID 25268620, 2014).
end stage renal disease (3 papers, 2016 to 2020). "Meta-analysis of genome-wide association studies for DKD revealed novel association (P = 1.2 × 10–8) with SNPs in the AFF3 gene, a transcriptional activator that influences renal fibrosis through the TGFβ1 pathway, in individuals who had progressed to end stage renal disease." (PMID 33178681, 2020).
Obesity (3 papers, 2023 to 2024). Accumulation of substantial excess body fat. "Gene prioritisation considering SNP GERP scores, variant consequences, and allele comparison with other mouse lines identified seven novel obesity candidate genes: 4930441H08Rik, Aff3, Fam237b, Gm36633, Pced1a, Tecrl, and Zfp536." (PMID 38483771, 2024).
systemic lupus erythematosus (3 papers, 2021 to 2024). An autoimmune multi-organ disease typically associated with vasculopathy and autoantibody production. "It was further reported that, besides, its role in RA, the AFF3 gene shares the same genetic basis with the systemic lupus erythematosus (SLE)." (PMID 34104118, 2021).
glioma (2 papers, 2017 to 2024). A benign or malignant brain and spinal cord tumor that arises from glial cells (astrocytes, oligodendrocytes, ependymal cells). "We have also identified a four RBP (NOL3, SUCLG1, HERC5 and AFF3) signature, having a unique expression pattern in glioma stem-like cells (GSCs), to be an independent poor prognostic indicator in GBM." (PMID 28035070, 2017).
juvenile idiopathic arthritis (2 papers, 2021 to 2024). Juvenile idiopathic arthritis (JIA) is the term used to describe a group of inflammatory articular disorders of unknown cause that begin before the age of 16 and last over 6 weeks. "In addition, the AFF3 gene has been detected to be significantly associated (OR: 1.25 (1.13–1.39); P = 2.05 × 10−5) with juvenile idiopathic arthritis (JIA) as well." (PMID 34104118, 2021).
type 2 diabetes (2 papers, 2022 to 2024). "AFF3 (AF4/FMR2 family, member 3) was recognized as a master regulator of metabolic inflexibility in type 2 diabetes and was associated with serum lipid alterations and blood triglyceride levels." (PMID 38483771, 2024).
adrenocortical tumours (1 paper, 2024). "Both AFF3 and ISM1 are known to be overexpressed in benign and malignant adrenocortical tumours with CTNNB1 mutation." (PMID 39167619, 2024). "Of note, in the two samples with an abundance of AC1, we have observed a high expression of AFF3, ISM1 and LEF1, all known CTNNB1 target genes in both benign and malignant adrenocortical tumours." (PMID 39167619, 2024).
Arthritis (1 paper, 2025). Inflammation of a joint. "Interestingly, in response to DMM injury, LG/J mice develop robust synovial and meniscal calcification, correlated with SNPs relating to angiogenesis, bone metabolism/calcification, arthritis, and ankylosing‐spondylitis and gene transcripts of Aff3, Fam81a, Syn3, and Ank." (PMID 39930949, 2025).
breast tumors (1 paper, 2018). "Clinical analysis showed that increased AFF3 expression in ER+ breast tumors was associated with worse overall survival." (PMID 30326937, 2018).
cervical cancer (1 paper, 2021). A primary or metastatic malignant neoplasm involving the cervix. "The result shows that POLR2J2, RBFOX3, RBMS1, ADARB1, AFF3, CSDC2 and CTIF were down-regulated in most of cervical cancer tissues compared with corresponding normal cervix tissues." (PMID 34863153, 2021).
chronic lymphocytic leukemia (1 paper, 2012). "Recently, the CDK9 inhibitor flavopiridol was shown to induce apoptosis in primary chronic lymphocytic leukemia by targeting CDK9, cyclin T1, AFF3/4 and MLLT1." (PMID 23140174, 2012).
Cognitive impairment (1 paper, 2024). Abnormal cognition is characterized by deficits in thinking, reasoning, or remembering. "We present evidence suggesting that multiple AFF3 variant-specific mechanisms are associated with cognitive impairment." (PMID 38811945, 2024).
esophagitis (1 paper, 2025). An acute or chronic inflammatory disease affecting the esophageal wall. "A Yates-corrected Chi-square test revealed the association between AFF3 variants and cutaneous, articular, and vascular impairment, ILD, and esophagitis (χ2 = 19.1–44.8, p < 0.0001); a weak association was found with Sjögren’s syndrome (χ2 = 7.4, p < 0.001)." (PMID 41283471, 2025).
hepatocellular carcinoma (1 paper, 2024). A malignant tumor that arises from hepatocytes. "For example, UHRF1 in hepatocellular carcinoma (HCC) 19, CXCL11 in colorectal cancer (CRC) 20, AFF3 in GC 21, and so on." (PMID 38706903, 2024).
KINSSHIP syndrome (1 paper, 2024). A syndrome characterized by developmental delay, impaired intellectual development, seizures, mesomelic dysplasia, dysmorphic facial features, horseshoe or hypoplastic kidney, and failure to thrive that has material basis in heterozygous mutation in AFF3 on chromosome 2q11.2. "While repeat expansion in the promoter and de novo dominant-negative variants in the degron of this gene were previously linked to mild ID and KINSSHIP syndrome, respectively, we show that duplication, truncation, deletion, ablation, and biallelic variants in AFF3 are also associated with ID." (PMID 38811945, 2024).